CD4 (CD4 molecule)
Diseases named in the same sentence as CD4 in open-access papers (continued):
Sharing a sentence is not in itself a finding about the gene and the disease.
breast cancer (continued). "Previously, we showed that the co-blockade of PD-1 and PD-L1 upregulated the surface expression of CTLA-4, TIM-3, and LAG-3 on CD4+ T cell subsets by using a co-culture system with human breast cancer cell lines." (PMID 32616706, 2020). "TILs are comprised primarily of CD8 + and CD4 + T cells, and higher CD8 + T cells infiltration levels were associated with more favorable overall response rates in breast cancer." (PMID 33193702, 2020). "Similar changes were seen in human specimens collected from patients with unilateral upper extremity breast cancer-related lymphedema, where the number of tissue-infiltrating CD4+ T cells was positively correlated with severity of disease." (PMID 32268536, 2020). "The results suggested that CXCL9/10/13 expressions were significantly associated with infiltrating levels of B cells, CD8+ T cells, CD4+ T cells, neutrophils, and DCs in breast cancer, while CXCL12 was conversely correlated with macrophages." (PMID 32963527, 2020). "Immune response to trastuzumab treated HER2 + breast cancer was shown to be impacted by CD4 + T-cell stimulation." (PMID 33292267, 2020). "The adoptive transfer of CD4+CD45RBloCD25+ cells from mice exposed to L. reuteri is sufficient to regress tumors in a transgenic breast cancer model." (PMID 32354130, 2020). "We also investigated the CD4/CD8, CD8/FOXP3, and FOXP3/CD4 ratio because there have been several studies that reported the CD8/FOXP3 ratio in breast cancer." (PMID 32222891, 2020). "A loss of predominance of Ki67+ tumor cell fraction was associated with the predominance of tumor infiltrating CD4+ and CD8+ Te subsets in all animals with mammary carcinoma." (PMID 33115528, 2020). "In this study, we aimed to examine the effects of this recombinant protein on CD4+CD25+/CD4+ proportion in the spleen of 4T1 mammary carcinoma-bearing BALB/c mice." (PMID 32306719, 2020). "In breast cancer patients and a mouse lymphoma model, dormant DTCs have been observed to persist in the bone marrow along with a rise in CD4+ and CD8+ T cells, indicating that in addition to CD8+ T cells, CD4+ T cells also played a role in cancer dormancy." (PMID 31297335, 2019). "We propose that PIP from breast cancer cells binds to its putative receptor on dendritic cells, leading to increased production of IL-12, which enhances CD4+ Th1 differentiation and IFN-γ production." (PMID 31366131, 2019). "Remarkably, this correlated with CD4+ T-cell recruitment to the tumor site in breast cancer patients." (PMID 31849934, 2019). "CD4 memory-activated T cells facilitated tumor growth, whereas B cells, plasma cells, and NK cells inhibited tumor growth in breast cancer." (PMID 31799941, 2019). "In a previous study, we have detected a chronic inflammatory breast cancer microenvironment enriched with a high frequency of T helper cells (CD4+ T cells) that are considered to be important immune players within the tumor microenvironment." (PMID 31145753, 2019). "We determined the kinetics and level of expression of key inhibitory ICs (PD-1, CTLA-4, TIM-3 and LAG-3) and Treg-related markers (FoxP3 and Helios) in CD4+ T cells in the absence or presence of breast cancer cells." (PMID 31614877, 2019). "In a Her2-positive breast cancer model in mice, one study found that bulk “memory” CD4+ T cells from viral immune-oncotherapy cured tumor-bearing mice proliferated upon either in vivo or in vitro challenge." (PMID 31379821, 2019). "We also explored the impact of lactate on the ability of pDCs to induce Tregs and implicated lactate-induced modulation of tryptophan metabolism in pDCs in the expansion of CD4+ FoxP3+ Tregs in breast cancer." (PMID 31440253, 2019). "BRCA2-deficient breast cancers in WSI were enriched for activated CD4 T cells, γδ T cells, type 1 T helper cell, activated B cells, and immature B cell compared to BRCA-proficient breast cancers." (PMID 31022191, 2019).
breast cancer (continued). "Next, we examined the effect of anti-PD-1, anti-PD-L1 or both mAbs on the expression of ICs, FoxP3 and Helios in CD4+CD25+ T cells in the presence of breast cancer cells." (PMID 31614877, 2019). "The combinations of ICs upregulated by breast cancer cells differed from one cell line to another, and across the different CD4+ T cell subsets." (PMID 31614877, 2019). "IL-16, a cytokine known for its chemotactic and inflammatory properties, induces proliferation in cutaneous T-cell lymphoma T cells and plasma cells in multiple myeloma and recruits CD4+ protumor macrophages in breast cancer." (PMID 31737562, 2019). "In the tumor microenvironment, reduced numbers of effector immune cells, especially activated memory CD4+ T cells and activated mast cells, facilitate breast cancer metastasis to the lymph nodes." (PMID 30670769, 2019). "Based on our analyses, it is worth determining the proportions of M0 macrophages, resting memory CD4+ T cells and γδ T cells in all breast cancer patients." (PMID 31762828, 2019). "This analysis showed increased baseline levels of PD-1 on CD4 T cells, and PD-L1 on circulating monocytes of breast cancer patient samples, as compared to HD." (PMID 31296256, 2019). "This approach has been applied to a multitude of research areas including clinical studies of colorectal cancer, ovarian cancer, and breast cancer and basic research studies such as naïve CD4 T cells and B cells." (PMID 31049047, 2019). "High CD4/CD8 ratios have been associated to worse prognosis in patients with different types of cancer, including breast cancer, suggesting higher proportion of CD4+ Treg cells." (PMID 31762937, 2019). "As an example, in breast cancer patients, peptide vaccination using the E75 peptide in combination with GM-CSF in breast cancer patients was able to activate both naïve CD4+ T cells as well as memory-phenotype CD4+ T cells specific for the tumor." (PMID 31379821, 2019). "We investigated the effect of anti-PD-1, anti-PD-L1 or both mAbs on the expression of ICs, FoxP3 and Helios in CD4+CD25− T cells in the presence of breast cancer cells." (PMID 31614877, 2019). "We have previously detected a significant elevation in the proportion of CD4+ T cells drained from the tumor microenvironment of breast cancer patients through axillary tributaries in comparison with peripheral blood." (PMID 31145753, 2019). "The median CD4 count among HIV-infected patients with breast cancer was 396 cells/mm3 (IQR 209 cells/mm3–525.6 cells/mm3)." (PMID 31649747, 2019). "Our findings showed that increased DFS was directly correlated with an increase in resting and activated memory CD4+ T cells in breast cancer, indicating the anti-tumor properties of memory CD4+ T cells." (PMID 31762828, 2019). "A study focusing on breast cancer (84 cases) reported an infiltration of BrM by CD4+ and CD8+ T cells in 96 and 98% of cases, respectively." (PMID 31824260, 2019). "In breast cancer patients, fewer intratumoral and stromal CD4+ and CD8+ TILs were observed in BrM as compared to the primary tumor or to metastatic cancer lesions at other sites." (PMID 31824260, 2019). "As seen for HCMV-specific CD8+ T cells and CD4+ T cells from rheumatoid arthritis, lymphocyte populations from patients with breast carcinoma, as annotated in the original study, recapitulated the innateness gradient." (PMID 30737409, 2019). "A previous study demonstrated a significant role for CD4+ T cells as enhancers of lung metastases from breast carcinomas by preventing the reduction or destruction of malignant cells due to the cytotoxic mechanisms present in CD4+ T cells." (PMID 30922347, 2019). "Combination therapy with anti-PD-1 and VIPhyb treatment suppressed breast cancer growth and enhanced proliferation of antigen experienced CD4+ T cells." (PMID 30400835, 2018).
breast cancer (continued). "We applied the TIMER tool to investigate tumor purity and the infiltrating immune cell landscape of breast cancer (B cells, CD4+ T cells, CD8+ T cells, neutrophils, macrophages and dendritic cells) in the context of mRNA expression of our target genes." (PMID 29796177, 2018). "The importance of cluster of differentiation 8 (CD8)-positive (CD8+) cytotoxic T cells is well-established in breast cancer, and CD4+ T cells have a central role in orchestrating antitumoral immunity." (PMID 29482642, 2018). "Collectively, these results demonstrate, for the first time, that the depletion of HSC-associated a2V leads to a reduction of CD4+ and CD8+ T cells in the periphery that promotes breast cancer growth and metastasis." (PMID 30237863, 2018). "We report seven women with breast cancer, with a median CD4 count of 481 cells/μL and undetectable median viral load." (PMID 30368240, 2018). "There is ample evidence that a pCR in the primary breast cancer following NAC is significantly associated with high levels of tumour infiltration by TILs, CD4+ and CD8+ T effector cells, CD56+ NK cells and high CD8+: FOXP3+ T cell ratios." (PMID 29390966, 2018). "While most CXCL13+ T cells in breast cancer samples are CD4+ T cells, a subset of tumor-infiltrating CD8+ T cells was also noted to produce CXCL13 and reside near B cell follicles, albeit with lower CXCL13 expression than in CD4+ T cells." (PMID 30190721, 2018). "In breast cancer, the frequency of CD4+CD25+FoxP3+ regulatory T cells was inversely correlated with clinical outcomes." (PMID 28669079, 2018). "Median CD4 count was the lowest in germinal tumors (117 cells/μL) and the highest in women with breast cancer (890 cells/μL); median viral load was < 40 copies/mL in nearly all patients with neoplasms, except for germinal and head-and neck-tumors." (PMID 30368240, 2018). "Further studies are warranted to explore the immunomodulatory effects of phenotypes of CD4+ T cell subsets in breast cancer." (PMID 30069490, 2018). "Breast cancer tumors are infiltrated with CD4+ T cells secreting IFN-γ and IL-13 while breast cancer instructs dendritic cells to prime IL-13-secreting CD4+ T cells that facilitate tumor development." (PMID 30648081, 2018). "Detailed studies of breast cancer tissue have also revealed a population of infiltrating CXCL13+ CD4+ T cells." (PMID 30190721, 2018). "This study aimed to investigate the correlation of CD4+/PD-1+ or CD4+/PD-1− tumor-infiltrating lymphocytes with pathological characteristics in breast cancer patients." (PMID 30069490, 2018). "The clinical importance of tumor-infiltrating cluster of differentiation 4 (CD4) T cells is incompletely understood in early breast cancer." (PMID 29482642, 2018). "Our results suggest that Tregs in human breast cancer are mainly converted from naive PB CD4+ T cells, recruited by TAM-derived CCL18." (PMID 28290464, 2017). "In early time, the risk of breast cancer in the population with AIDS had been lower than in the general population, with small variations in incidence relative to the CD4 count or duration of infection." (PMID 29021819, 2017). "Our studies demonstrated that following Mam-A cDNA vaccination, there was an upregulation of tumor lytic CD4+ ICOShi T-cells in Mam-A vaccinated breast cancer patients and also induction of antigen specific CD8+ T-cell effector responses." (PMID 28304339, 2017). "In human breast cancer xenografts in humanized mice, blocking the recruitment of naive CD4+ T cells into tumor by knocking down the expression of PITPNM3, a CCL18 receptor, significantly reduces intratumoral Tregs and inhibits tumor progression." (PMID 28290464, 2017). "Further, in the same cohort, the ICOS expression on CD4+ T-cells remained constant (approximately 21%) in breast cancer patients prior to and following vaccination similar to that seen in normal subjects." (PMID 28304339, 2017).
breast cancer (continued). "The TCR sequences of TI Tregs and the same subsets of PB CD4+ T cells were compared in a larger group of 23 breast cancer patients by studying the TCR sequences of a single VβJβ gene rearrangement (TRBV12-4/TRBJ1-2)." (PMID 28290464, 2017). "Significance of this analysis is exemplified by the fact that mutations of BTLA, CD28, CD4, and CD8A genes in the GO term cell surface receptor-linked signal transduction contribute to sporadic breast cancer risk." (PMID 27911271, 2017). "Low peripheral blood CD4+ counts have been observed even in the early stages of breast cancer patients." (PMID 29061183, 2017). "Among CD4+ T‐cell subpopulations, increased prevalence of Tregs has been reported in the TDLNs in breast cancer patients." (PMID 28993429, 2017). "Our findings in human samples are in agreement with previous reports that Tregs in murine breast cancers are derived from resting CD4+ T cells." (PMID 28290464, 2017). "We then showed that naive CD4+ T cells from the PB of breast cancer patients differentiate in vitro into functional Tregs by exposure to autologous DCs and CM from their tumors." (PMID 28290464, 2017). "In this study, the gene expression profiling of four subsets of T CD4+ cells was investigated in the four different stages of breast cancer." (PMID 29299026, 2017). "Patients with circulating breast cancer cells have been shown to have a significant increase in Fas+ CD4+ T helper cells, opening the door for immune escape and worsening disease prognosis." (PMID 27766079, 2016). "Preliminary results from our laboratory, show increased numbers of CD8+ and CD4+ lymphocytes in rTcCRT-treated mammary tumor bearing mice." (PMID 27619675, 2016). "In our study, the breast cancer tissue samples tested had increased T cell and macrophage immune cell marker (CD4, CD25, CD63, CD163) expression compared to benign tissue." (PMID 26964534, 2016). "In addition, transgenic mouse models of breast cancer that are deficient in CD4+ cells initially developed primary tumors at similar rates but developed lung metastasis at a lower frequency than wildtype mice, suggesting that CD4 + T cells are required for breast cancer during lung metastasis." (PMID 26964534, 2016). "For HER2+ breast cancers, type 1 T-cells, either increased TBET+ tumor infiltration or increased type 1 HER2-specific CD4+ T-cells in the peripheral blood, are associated with better outcomes." (PMID 27777769, 2016). "For CD4+ T cells, this change has been reported previously in breast cancer patients, although we have expanded the observation to recent thymic emigrants, while for B cells, this is – to our knowledge – a new observation." (PMID 26810608, 2016). "For example, in human breast cancer a CD68 high/CD4 high/CD8 low T-cell signature is significantly correlated with reduced patient survival." (PMID 25884510, 2015). "Additional evidence supporting different roles of CD4+ and CD8+ T cells in the pathogenesis of breast cancer includes the dynamics of CD4/CD8 proportions with progression of tumor development." (PMID 25968569, 2015). "The results suggest that Th17 cells become a dominant CD4+ T cell population in TILs of breast cancer." (PMID 25968569, 2015). "Our findings from mouse breast cancer models suggested that both CD4+ and CD8+ T cells significantly infiltrated into tumor sites." (PMID 25968569, 2015). "Taken together, our studies suggest that CD4+ T cells have dynamic roles and subset distributions during breast cancer development and progression." (PMID 25968569, 2015). "To further confirm the role of CD4+ and CD8+ T cells in human breast cancer development and progression, we assessed CD4+ and CD8+ T cells, as well as IL-17+ and Foxp3+ cells in breast tumor tissues from cancer patients using the immunohistochemical staining." (PMID 25968569, 2015). "Consistent with our results, it has been shown that the CD4+/CD8+ ratio in dLN was decreased with metastasis of tumor cells in breast cancer patients." (PMID 25605488, 2015).
breast cancer (continued). "This study aimed to assess the prognostic value of CD4+CD25+ T lymphocyte in peripheral blood among breast cancer patients treated with adoptive T lymphocytes immunotherapy." (PMID 26462021, 2015). "To test this possibility, we evaluated the dynamic distributions of CD4+ T cell subsets based on their proportions and relative cell numbers per tumor size at different stages of cancer development in these two breast cancer models." (PMID 25968569, 2015). "Clinicopathological factors of breast cancer patients were retrospectively analyzed relative to the levels of the intra-tumoral CD4+ and CD8+ T cells as well as CD4/CD8 ratios." (PMID 25968569, 2015). "In the current study, we provided critical information regarding CD4+ T cells in the immunoeditting process during breast cancer development and progression both in animal models and in cancer patients." (PMID 25968569, 2015). "We first showed that numbers of CD4+ T cells are significantly increased with breast cancer development, suggesting an active involvement of tumor-induced immune responses." (PMID 25968569, 2015). "In contrast, CD4+ T cell infiltration was inversely correlated with RFS (p = 0.07) of breast cancer patients." (PMID 25968569, 2015). "A mouse tumor model of mammary carcinomas demonstrated that IL-4-expressing CD4+ T cells indirectly promote the invasion and metastasis of mammary adenocarcinomas by promoting the protumor function of TAMs." (PMID 26242181, 2015). "The typical TIL populations found in most breast cancers are T cells (60%–90%, mostly CD4+), B cells (about 20% or less), monocytes (less than 10%), and NK cells (less than 5%)." (PMID 24762633, 2014). "A previous study revealed that Bregs in the lung metastasis from breast cancer were able to induce conversion of resting CD4+T cells to Tregs to support metastatic growth." (PMID 25381811, 2014). "While most breast cancers have CD4+ T cells as their dominant TIL, approximately 20%–25% have B cells as the major immune cell population." (PMID 24762633, 2014). "Other work has shown the predominance of the CD4 population over CD8 in breast cancer, and has suggested that CD8 cytotoxicity is minimal in untreated tumors." (PMID 25432519, 2014). "In this work, we show that the pre-treatment profile of immune cell subpopulations is able to identify a highly responsive group of breast carcinomas characterized by a high CD4, CD68 and CD20 and a low CD8 infiltration." (PMID 25432519, 2014). "Decreased NK cell activity, decreased frequency of myeloid dendritic cells in circulating activated T lymphocytes, and higher level of CD4+ T cells that increased in response to stress were observed in fatigued breast cancer survivors." (PMID 23959120, 2013). "We then applied our method to reconstruct signaling downstream of CD3, CD28 and LFA-1 in CD4 T-cells, as well as signal transduction in the ErbB pathway in breast cancer cells." (PMID 23935958, 2013). "We then apply our approach to study the intracellular signaling of human primary nave CD4+ T-cells, as well as ErbB signaling in trastuzumab resistant breast cancer cells." (PMID 23935958, 2013). "In a mouse model of spontaneous mammary carcinoma, the depletion of Tregs resulted in CD4+ T-cell activation and subsequent development of efficient CD8+ T-cell activity." (PMID 22890822, 2013). "A tissue microarray (TMA) including 894 ductal and 164 lobular breast cancers was stained with antibodies recognizing CD4, FOXP3, and IL-17 by standard immunohistochemical techniques." (PMID 22471961, 2012). "For example, Bregs in the lung metastasis from breast cancer have been reported to induce conversion of resting CD4+T cells to Tregs to support metastatic growth." (PMID 22272696, 2012). "Ductal breast cancers displayed a higher CD4+ lymphocyte total (18.2 ± 25.3 vs. 11.1 ± 19.4; p = 0.014) and intratumoral infiltration as compared to lobular tumors (12.6 ± 20.3 vs. 6.8 ± 14.1, p = 0.008)." (PMID 22471961, 2012).